ENSG00000267001 (novel protein)
Gene: Protein-coding gene on chromosome 19 (2,717,769 to 2,740,048, reverse strand). Ensembl gene ENSG00000267001.
Genetic constraint (gnomAD): Loss-of-function variants: 2 observed, 4.81 expected, observed/expected ratio (o/e) 0.42, 90% interval 0.17 to 1.29. That is too few expected variants to judge how well the gene tolerates losing a copy. Missense variants: 142 observed, 133.55 expected, observed/expected ratio (o/e) 1.06, 90% interval 0.93 to 1.22. Synonymous variants: 68 observed, 61.89 expected, observed/expected ratio (o/e) 1.1, 90% interval 0.9 to 1.34.